ENSG00000274015 (novel transcript)
Synonyms: LOC105370532
Gene: Long non-coding RNA gene on chromosome 14 (63,641,745 to 63,665,593, forward strand). Ensembl gene ENSG00000274015.
Gene Ontology:
Biological process: RNA processing
Cellular component: nucleolus